ENSG00000286070 (novel protein)
Gene: Protein-coding gene on chromosome 22 (24,556,007 to 24,628,987, forward strand). Ensembl gene ENSG00000286070.
Genetic constraint (gnomAD): Missense variants: 73 observed, 173.4 expected, observed/expected ratio (o/e) 0.42, 90% interval 0.35 to 0.51. Synonymous variants: 66 observed, 61.38 expected, observed/expected ratio (o/e) 1.08, 90% interval 0.88 to 1.32.